CD27 (CD27 molecule)
Diseases named in the same sentence as CD27 in open-access papers (continued):
Sharing a sentence is not in itself a finding about the gene and the disease.
COVID-19 (continued). "The SARS-CoV-2-specific response in the IgDlo B cell (CD20+ CD38int-lo) population was divided between conventional (CD27+) and double negative (CD27-) memory B cells, with both populations displaying similar kinetics in COVID-19-naïve PAD patients and healthy donors." (PMID 36618402, 2022). "Interestingly, resting memory B cells, characterized by frequencies of CD19+CD20+CD10-IgD-CD38-CD21+CD27+ cells were significantly decreased in moderate and severe COVID-19 both HD and non-HD patients." (PMID 35265078, 2022). "Recovered COVID-19 donors had similar levels of CD21+CD27+ non-plasmablasts as the HD group." (PMID 32669287, 2020). "Accordingly, the hierarchical clustering analysis shows that most critical COVID-19 patients aberrantly display high proportions of ASC, DN3, and SwM B cells in a similar trend that severe patients exhibited high proportions of DN2, atypical CD27- switched memory, and actN." (PMID 33343585, 2020).
systemic lupus erythematosus (59 papers, 2008 to 2026). An autoimmune multi-organ disease typically associated with vasculopathy and autoantibody production. "A previous study showed that CD27- switch memory B cells from normal subjects and systemic lupus erythematosus (SLE) patients had substantial levels of Ig mutations but lower than conventional CD27+ switch memory B cells." (PMID 19804628, 2009). "CD27 is a general marker of memory B cells, and CD27+ B cells are more susceptible to apoptosis than CD27− B cells in common variable immunodeficiency and lupus patients." (PMID 28439273, 2017). "Importantly, CD27 expression by B cells has been considered a hallmark for cells that have undergone somatic hypermutation, although recently a CD27- population of memory B cells with mutated Ig genes has been described, which is elevated in patients with systemic lupus erythematosus (SLE)." (PMID 19500335, 2009). "Lower expression of the inhibitory receptor Fc fragment of IgG receptor IIb (FcγRIIB) has been observed on circulating CD27+ B cells and circulating marginal zone B cells in systemic lupus erythematosus (SLE)." (PMID 39435875, 2025). "Rather, differential chromatin accessibility in lupus results from widespread changes to accessibility within all subpopulations of CD45RA+CD27+CD4+ T cells, including true naive Th cells." (PMID 39688922, 2024). "Human ABC-like B cells (including CD27–IgD– and CD11c+CD21lo) are more abundant in various human autoimmune diseases, such as systemic lupus erythematosus (SLE), and rheumatoid arthritis (RA)." (PMID 37841260, 2023). "We also examined a subset of CD11c+CD21– ABCs that lacks both CD27 and IgD expression (CD11c+CD21–CD27–IgD–), called “DN2,” that is prevalent in lupus and can produce disease-associated antibodies." (PMID 37129971, 2023). "In the present study, we evaluated the ability of αIL-21R to restrain B cell differentiation and function and found that the generation of CD27+CD38hi plasmablasts was reduced in the cTFH–B cell co-culture gained from lupus patients and control individuals." (PMID 36293075, 2022). "CD27-IgD-CXCR5- (DN2) B cells are capable of differentiating into plasma cells induced by IL-21 in lupus patients." (PMID 34168653, 2021). "In contrast, studies have reported that the CD27− naïve B-cell subpopulation is markedly reduced in the peripheral blood of lupus patients." (PMID 28387859, 2017). "Existing heterogeneity among flow cytometry–defined CD45RA+CD27+ Th cells is maintained in lupus." (PMID 39688922, 2024). "IgD and CD27 double negative B (DN-B) cells constitute a heterogeneous group of B cells, which is initially described in association with aging and systemic lupus erythematosus." (PMID 39015296, 2024). "It has been reported that CD27 may lead to anxiety or depression in patients with systemic lupus erythematosus by regulating T cells." (PMID 36561317, 2022). "IgD+CD27+ unswitched MBCs usually present anti-inflammatory properties, for instance, are reduced in systemic lupus erythematosus, primary Sjögren’s Syndrome (pSS), and reconstitute after immunosuppressive treatment, this phenomenon also is observed in IgG4-RD in our study." (PMID 34603334, 2021). "However, concurrent infection in these patients with elevated CD27 expression in their plasma cells limits the clinical utility of CD27+ plasma cell level as an ideal marker of lupus disease activity." (PMID 24000287, 2013). "Expansion of a novel CD45RA+CD27+ antigen-experienced population among lupus naive T cells or shifts in the frequencies of naive Th cell subpopulations could explain this result and potentially indicate that quiescent true naive T cells are unaltered in disease." (PMID 39688922, 2024). "After 24 h of DW treatment, there was a noticeably decrease in frequency of CD19+ cells and increase in frequency CD19+ CD24+ CD27+, CD19+ CD24+ CD27+ IL-10+ Breg memory cells and CD19+ IL-10+ Bregs compared with untreated cells (lupus)." (PMID 40158179, 2025).
systemic lupus erythematosus (continued). "In systemic lupus erythematosus (SLE) patients, the upregulation of CD38 expression in marginal zone-like IgD + CD27 + B cells has been reported, and the depletion of CD38 in pristane-induced lupus mouse model significantly improve the symptom." (PMID 36426217, 2022). "Compared with CD27++CD20−CD19dim cells, HLA-DRhiCD27hi PBs show a closer correlation with lupus and anti-dsDNA levels." (PMID 32280720, 2020). "In contrast to individuals with rheumatoid arthritis or systemic lupus erythematosus, we found that expression levels of CD24 and CXCR3 on switched CD21+CD24+CD27+CD38intCD95+IgD− memory B cells were reduced in individuals with long-standing diabetes." (PMID 29881878, 2018). "A subset of CD27+CD25high Vδ1 T cells, expressing FoxP3 similarly to regulatory CD4+ T cells, was reported in patients with systemic lupus erythematosus (SLE)." (PMID 28713381, 2017). "To better define TFH-B cell dialogue in lupus, we investigated the expression of IL-21R by B cells analyzed by three-color cytometry using anti-CD19, anti-CD27 and anti-IgD Abs." (PMID 24069401, 2013). "Overall, these results indicated that the accumulation of hyperactivated CD19hi CD27– “atypical naive” B cells, easily identified, was associated with SLE disease activity in lupus patients undergoing hemodialysis as in non-dialyzed patients." (PMID 40453547, 2025). "Double negative B cells (DNB), marked by their CD27 and IgD negativity, have been shown to be elevated in systemic autoimmune diseases such as systemic lupus erythematosus (SLE) and antiphospholipid syndrome (APS), and associated with renal impairment, suggesting a pathogenic role in autoimmunity." (PMID 38707902, 2024). "To examine these alternative hypotheses, we generated single-cell multiome chromatin accessibility and nuclear RNA data from sorted CD45RA+CD27+CD4+ T cells in 3 healthy and 6 lupus participants." (PMID 39688922, 2024). "SERPINB3 was shown to be expressed on CD27+ B lymphocyte surface of healthy donors, while it was absent on CD27+ cells of lupus patients." (PMID 30254646, 2018). "Lupus patients had significantly increased proportions of activated B cells, as demonstrated by the increased percentage of CD20+ cells with elevated levels of CD69 and increased proportion of CD86+ cells in the CD27+ B-cell compartment." (PMID 18783591, 2008). "In systemic lupus erythematosus (SLE), we observed a significant skew in the usage of VDJ genes, particularly in CD27+IgD+ unswitched memory B cells and plasmablasts." (PMID 38361948, 2024). "Interestingly, an earlier study identified a CD19+IgD-CD27- double negative (DN) B cell population, which was phenotypically and functionally similar to CD27+ memory B cells, in patients with systemic lupus erythematosus (SLE)." (PMID 37475856, 2023). "Moreover, overexpression of CD27 and its soluble form and surprisingly also a higher expression of CD70 have been documented in several types of autoimmune disorders including systemic lupus erythematosus, rheumatoid arthritis, multiple sclerosis, and psoriasis." (PMID 33996677, 2021). "In addition, we found that the expression of CD27, Anxa9, CCR9, and IL17Rβ were decreased in M-MDSCs from pristane-induce lupus mice, and INK128 could increase the expression of these genes." (PMID 34282122, 2021). "DN B cells were further divided into two subgroups in a previous study on systemic lupus erythematosus (SLE), DN1 cells (CXCR5+ CD19+ IgD-CD27-) and DN2 cells (CXCR5- CD19+IgD- CD27-)." (PMID 34394101, 2021). "It has been reported that patients with systemic lupus erythematosus, who are characterized by elevated type-I IFN levels, have a higher representation of peripheral transitional B cells, together with higher numbers of plasmablasts and an expanded population of CD27-IgD- memory B-cell subset." (PMID 27281019, 2016).
systemic lupus erythematosus (continued). "Previous studies demonstrated CD27+IgD+ unswitched memory B cells were innate-like B cells and could produce protective natural IgM in RA, whereas CD27−IgD− double negative B cells exacerbated systemic lupus erythematosus (SLE) patients and were linked to renal impairment." (PMID 37143367, 2023). "IgD+CD27+ nonswitched memory B cells with anti-inflammatory properties, for instance, are reduced in systemic lupus erythematosus (SLE) and reconstitute after immunosuppressive treatment." (PMID 30285841, 2018). "Severe COVID has shown striking similarity to systemic autoimmunity seen in systemic lupus erythematosus (SLE), with marked extrafollicular B cell maturation and autoimmune autoantibody production by double-negative (CD27- IgD-) B cells." (PMID 37153597, 2023). "B cells that are double negative for CD27 and IgD, express CD11c, and are negative for CXCR5 (DN2 cells) have been described to be autoreactive and expanded in lupus." (PMID 37492569, 2023). "This review focuses on ABC and ABC-like sub-populations found in Systemic Lupus Erythematosus (SLE) patients (such as the double negative 2;DN2 population: CD19+,IgD−,CD27−, CXCR5−,T-bet+) and broaches the subject of their potential use as prognostic and/or diagnostic markers." (PMID 33163863, 2020).
viral infections (47 papers, 2009 to 2025). "Even more, numerical and/or functional impairments in CD24+CD38+ or CD24+CD27+ Bregs were also implicated in autoimmunity (rheumatoid arthritis, psoriasis, systemic sclerosis), viral infection (hepatitis B virus), and allergy (allergic rhinitis)." (PMID 36685568, 2022). "Unlike naive T cells, G9a has been proposed to repress expression of CD25 and CD27, cell surface receptors that are associated with cell activation and proliferation, in memory T cells during viral infection." (PMID 28443098, 2017). "CD27 is a costimulatory receptor on T cells that is lost from effector memory cells in some viral infections and whose loss is often associated with a more differentiated effector cell phenotype." (PMID 22132212, 2011). "Our data suggested that NFATc1 signaling promotes KLRG1+CD27- T cell differentiation and memory inflation during chronic virus infection." (PMID 38346075, 2024). "Datasets from the Immunological Genome Project (ImmGen) mouse database show that Kcnj8 is highly expressed in spleen CD27-/CD11b+ NK cell subsets and, upon viral infection, is strongly upregulated in cytotoxic CD8+ T cells." (PMID 39687626, 2024). "It was reported that mature NK cells (NK1.1+ CD11b+) expressing Ly6C present a resting/inert phenotype with a poor proliferative potential, and that memory NK cells express high levels of Ly6C (and low levels of CD27) upon viral infection." (PMID 34741509, 2022). "These CD4 TEMRA cells are more frequent in patients with some viral infections, such as dengue virus or cytomegalovirus, and they show a decreased CD27 expression but an increased expression of effector molecules." (PMID 33572562, 2021). "This also suggests that although several other T-cell co-stimulation pathways exist, such as the OX40/OX40L and 4-1BB/4-1BB-L pathways, the CD27/CD70 interaction has a unique functional role in fine-tuning T-cell-mediated immunity to virus infections." (PMID 33996677, 2021). "In conclusion, our results report unique TCF-1hi CD27+ NK cells with memory capacity and stem cell features after virus infection." (PMID 33370392, 2020). "In mouse models of viral infections, CD27 was assessed as the key factor in directing the autocrine production of IL-2 that is required for the long-term survival of CD8+ T cells in nonlymphoid tissues." (PMID 31623665, 2019). "Several other groups have previously linked CD27+ and CD90+ NK cells with increased IFN-γ production that protect against viral infections." (PMID 31337788, 2019). "Especially, CD27 promotes immune activation and enhances primary, secondary, memory, and recall responses toward viral infections." (PMID 31447833, 2019). "In peripheral blood, CD4+ T cells with low CD27, CD28, and CCR7 expression associate with viral infections and display cytotoxic functions." (PMID 30389931, 2018). "Results from patients with other neuroinflammatory disorders like multiple sclerosis, viral infections, or neurosyphilis showed that 85% of the total B cell population in the CSF are CD27+, in contrast to 31% in the peripheral blood." (PMID 20042073, 2009). "CD27+ IFNγ-producing γδ T cells defend against viral infection via directly killing infected cells." (PMID 38816652, 2024). "CD27+ plasmablasts are prevalent in the context of virus infection and autoimmune disease." (PMID 39340016, 2024). "In a previous report, Klrg1+ Cd27+ cells demonstrated robust cytotoxicity against viral infection." (PMID 37638012, 2023). "Furthermore, the level of CD27+CD38+ ASCs was found to be increased during acute viral infections or vaccination, but found to be only transiently detectable in the blood." (PMID 35898494, 2022). "As a co-stimulatory immune-checkpoint receptor, CD27 is constitutively expressed on a broad range of T cells, and co-stimulation of CD8+ T cells through CD27 promotes immune activation and enhances primary, secondary, memory and recall responses towards viral infections." (PMID 33154753, 2020).
viral infections (continued). "Therefore, stimulation of a γδTCR through a stress-induced ligand, such as EPCR, which occurs in viral infection, may differentiate CD27+Ly6C− γδ T cells into CD27+Ly6C+ γδ T cells." (PMID 38816652, 2024). "In the case of viral infections, an increased abundance of CD4+CD27-CD28+ cells may be an early indicator of the prioritized loss of CD27 in CD4+ T cells, with the eventual loss of the CD28 antigen as cells progress to a differentiated state, in contrast with CD8+ T cells." (PMID 38502582, 2024). "According to previous studies other sICs, such as CD27, CD40, and T cell exhaustion makers including TIM-3 have been reported to play significant roles in immune-mediated infection control in viral infections." (PMID 36045684, 2022). "Here we show that CD8+ T cells from burn injured mice have significantly reduced expression of CD27 and TCF1 1 week post-viral infection." (PMID 35505970, 2022). "Next, we analysed the expression of markers associated with T cell differentiation and memory formation (CD27, CD127, KLRG1) post-burn and viral infection." (PMID 35505970, 2022). "Hemagglutinin-specific B cells isolated this way from vaccinated human donors expressed elevated CD20, CD27, CD71, and CD11c, and reduced CD21, and their secreted antibodies blocked hemagglutination and neutralized viral infection." (PMID 31040853, 2019). "In models of viral infections, the accumulation and survival of virus-specific CD8+ T cells at the tissue site relied strongly on CD27/CD70 and to a lesser extent on 4-1BB and OX40 signaling." (PMID 31623665, 2019). "Following viral infection, Blimp-1 recruits G9a to repress expression of CD25 and CD27 and limit the expansion and proliferation of CD8 T cells." (PMID 28443098, 2017). "We consider that the relative increase in CD27- peripheral B cells could be originated by a B-cell exhaustion mechanism, where accumulation of peripheral blood CD27- tissue-like B cells is a consequence of persistent chronic immune activation (autoimmune disease) or persistent viral infections." (PMID 23800367, 2013). "Human CD8+ effector memory T cells observed in various virus infections have been subdivided further into “early”, “intermediate” and “late” based on differential expression of CD28 and CD27." (PMID 21124875, 2010). "CD27 also influences CD8+ T-cell responses, increasing the survival of these cells and contributing to the generation of primary and memory cells in the context of viral infections." (PMID 40006696, 2025). "CD38, CD161, CD27, CD127 and CCR7 are receptors that are extensively expressed on multiple lymphocyte subsets and have been demonstrated closely related to various diseases, including viral infections, autoimmune diseases and cancers." (PMID 40510360, 2025). "In a previous study investigating the impact of IRF4 downregulation on the functionality and expansion of CD8+ T cells during acute viral infections, CD8+ T cells with downregulated IRF4 levels exhibited CD27 upregulation and superior functionality as compared to wild type T cells." (PMID 37287982, 2023). "Previous study of Tmem cells using acute viral infection models have described CX3CR1neg cells as TCM (CD62L+, CD27+, CD127+), CX3CR1hi cells as TEM (CD62L−, CD27−, CD127−), and CX3CR1int cells as having phenotypic features more similar to CX3CR1neg cells (CD62L+/−, CD27+, CD127+)." (PMID 29669283, 2018). "B-1 B cells are characterized by the expression of the surface antigens CD20, CD27, as well as CD43, and play a key role in early protection against, and clearance of bacterial and viral infection via constitutive production of serum IgM referred to as “natural antibody”." (PMID 23251529, 2012). "Among the sICs, CD27 and CD40, which were identified as factors with high prognostic power through ML analysis in this study, play important roles in promoting the survival and effector functions of natural killer/T cells in viral infection, IFN-I response, and inhibition of its signaling." (PMID 39654974, 2024).
viral infections (continued). "The interplay among the TNFSF-TNFRSF of costimulatory molecules has been suggested to play a vital role for immune regulation, and a rational arrangement of costimulatory signals via OX40, 4-1BB, CD27 and GITR might be important for establishing protective T cell-immunity for virus infections." (PMID 37371066, 2023). "The function of these putative CD27- memory cells and their relationship to CD27+ cells is not well understood but increased frequencies have been observed during aging, in autoimmunity and several viral infections." (PMID 35572548, 2022). "For example, vaccinia virus vaccination was found to elicit long-lived memory cells that expressed intermediate levels of CD27 and lacked CD45RO, and yellow fever vaccination was found to elicit long-lived memory cells that expressed CCR7 and CD45RA." (PMID 37781376, 2023).